RN7SKP296 (RN7SK pseudogene 296)
Gene: Miscellaneous RNA gene on chromosome 3 (190,642,163 to 190,642,503, forward strand). Ensembl gene ENSG00000223117.
Homologues: Orthologues: chimpanzee 7SK (98% identical). Paralogues in human: RN7SKP162 (70% identical), 7SK (68% identical), RN7SKP217 (68% identical), RN7SKP180 (68% identical), RN7SKP184 (68% identical), RN7SKP79 (68% identical), RN7SKP124 (68% identical), RN7SKP127 (68% identical), RN7SKP133 (67% identical), RN7SKP176 (67% identical), RN7SKP25 (67% identical), RN7SKP30 (67% identical), and 283 more.